HNRNPUL2 (heterogeneous nuclear ribonucleoprotein U like 2)
Synonyms: SAF-A2; HNRPUL2; DKFZp762N1910
Tractability: PROTAC: ubiquitination databases record sites on it; its protein half-life has been measured.
Gene: Protein-coding gene on chromosome 11 (62,712,630 to 62,727,561, reverse strand). Ensembl gene ENSG00000214753.
Subcellular location: Nucleus
Subcellular location (Human Protein Atlas): Nucleoplasm
Gene Ontology:
Molecular function: RNA binding
Biological process: alternative mRNA splicing, via spliceosome
Cellular component: membrane; nucleoplasm; nucleus; synapse
Genetic constraint (gnomAD): Loss-of-function variants: 27 observed, 95.23 expected, observed/expected ratio (o/e) 0.28, 90% interval 0.21 to 0.39. The synonymous counts are far from expectation, so gnomAD's model fits this gene poorly and the ratio says little. Missense variants: 928 observed, 930.07 expected, observed/expected ratio (o/e) 1, 90% interval 0.94 to 1.05. Synonymous variants: 456 observed, 364.17 expected, observed/expected ratio (o/e) 1.25, 90% interval 1.16 to 1.35.
Homologues: Orthologues: chimpanzee HNRNPUL2 (99% identical), dog HNRNPUL2 (98% identical), rabbit HNRNPUL2 (98% identical), macaque HNRNPUL2 (97% identical), mouse Hnrnpul2 (95% identical), rat Hnrnpul2 (94% identical), pig HNRNPUL2 (88% identical), tropical clawed frog hnrnpul2 (45% identical), zebrafish si:ch211-107m4.1 (34% identical). Paralogues in human: HNRNPU (41% identical), HNRNPUL1 (40% identical).
Diseases named in the same sentence as HNRNPUL2 in open-access papers:
HNRNPUL2 is named in the same sentence as 9 diseases in open-access papers, as found by Europe PMC text mining. Sharing a sentence is not in itself a finding about the gene and the disease. The quoted sentences say what the papers report.
Cognitive impairment (1 paper, 2022). Abnormal cognition is characterized by deficits in thinking, reasoning, or remembering. "Autistic individuals with LoF variants in the four moderate-risk genes (NAV3, ITSN1, SCAF1 and HNRNPUL2; n = 95) have less cognitive impairment than 129 autistic individuals with LoF variants in highly penetrant genes (CHD8, SCN2A, ADNP, FOXP1 and SHANK3) (59% vs 88%, P = 1.9 × 10−6)." (PMID 35982159, 2022).
Intellectual disability (1 paper, 2022). "The absence of intellectual disability is also observed in other genes (for example, SCAF1, HNRNPUL2, GIGYF1, KDM5B and KMT2C) with substantial contribution from rare inherited variants and modest effect size." (PMID 35982159, 2022).
psychosis (1 paper, 2021). "HNRNPUL2 gene expression has also been shown to be significantly decreased in the blood of first episode psychosis patients, suggesting a neuronal functional role and that we may have under-ascertained individuals with neuropsychiatric phenotypes." (PMID 33874999, 2021).
Sepsis (1 paper, 2024). Sepsis is defined as life-threatening organ dysfunction caused by a dysregulated host response to infection. "Recent investigations have indicated that formononetin mitigates sepsis-induced organ damage by activating the hnRNPUL2/NLRP3 and PI3K/AKT pathways." (PMID 39549609, 2024).
cancer (4 papers, 2019 to 2026). A tumor composed of atypical neoplastic, often pleomorphic cells that invade other tissues. "CONCLUSION: Together, these findings point to an oncogenic role for lnc-HNRNPUL2 in CRC, which acts via miR-335-5p suppression, followed by a decrease in SFTPD mRNA that is involved in immune surveillance against several cancers." (PMID 41882606, 2026).
HNRNPUL2 also shares sentences with these, for which no sentence is quoted: colorectal cancer (2 papers); autism (1); benign adenoma (1); neurodevelopmental disorder (1).